IL6 (interleukin 6)
Diseases named in the same sentence as IL6 in open-access papers (continued):
Sharing a sentence is not in itself a finding about the gene and the disease.
Encephalopathy (continued). "The increase of inflammatory factors such as IL-6 found in SHM1-related encephalopathy leads to neurogenic inflammation, which may account for the fact that patients with FHM1/SHM1 often presented with non-infectious fevers." (PMID 33425808, 2020). "Elevations of IL-6, IL-10, and sTNFR1, but not IL-2, IL-4, and IFNγ,γwere associated with poor outcome in influenza-associated encephalopathy, with serum levels of cytokines usually higher than in the CSF." (PMID 33391257, 2020). "Indeed, elevated levels of IL-6, IL-8 (CXCL8), CCL2, and CCL4 have been reported in cerebrospinal fluid from patients with severe bronchiolitis and hRSV-associated encephalopathy." (PMID 30936869, 2019). "Although elevated serum IL-6 appears to have good predictive value for the clinical severity of influenza virus-associated encephalopathy, IL-6 measurements have not been performed in sufficient MERS cases for any conclusions to be drawn." (PMID 26499987, 2015). "IL-6 and TNF-α levels in the RSV-infected group were substantially elevated compared with that in the uninfected control group as the duration of RSV infection extended (P < 0.01), suggesting that encephalopathy-associated pro-inflammatory molecules are induced by RSV infection in N2a cells." (PMID 29427996, 2018). "IL-17, IL-6, IL-21, IL-22, IL-23, and TNF-α are inflammatory cytokines generated by Th17 cells, of which IL-17A is the most important cytokine in Th17-mediated encephalopathy." (PMID 36176437, 2022). "Inflammatory cytokines such as IL-6 and TNF-α are involved in the pathology of encephalopathy characterized by cytokine storm." (PMID 29725488, 2018). "Among these patients, elevated levels of IL-6 have been detected before HHV-6 reactivation and progression towards encephalopathy." (PMID 27538995, 2017). "During the acute stage of encephalopathy serum and cerebrospinal fluid concentrations of inflammatory cytokines such as tumor necrosis factor alpha (TNF-alpha), interleukin-1 (IL-1), and interleukin-6 (IL-6) become elevated." (PMID 28453565, 2017). "The systemic administration of Ig following HI encephalopathy significantly reduced the TNF-α, IL-6 and IL-1β mRNA expression levels in the ischemic tissue in the Ig + hypoxia group compared with those in the hypoxia group." (PMID 24520277, 2014). "In this survey, elevated levels of IL-6 in the cerebrospinal fluid, which were reported as a biomarker of neuro-BD, were observed in two HA20 patients presenting with aseptic meningitis or encephalopathy." (PMID 40574834, 2025). "Previous studies have reported that during influenza virus infection there is an increase in the levels of proinflammatory cytokines, such as IL-1β, IL-6, CXCL8, CXCL9, CXCL10, CCL2, and TNF-α, in the CSF of patients who present neurological alterations such as acute encephalitis and encephalopathy." (PMID 36591299, 2022). "These patients sometimes present anti-SARS-CoV-2 antibodies and inflammatory markers in the CSF, such as IL6 and IL8, suggesting encephalopathies could also result from viral infection in the brain [although comprehensive studies are currently lacking]." (PMID 33737867, 2021). "In our case, high levels of serum IL-6 and TNF-α were considered to be the cause of the encephalopathy; regrettably however, the blood flow was not examined." (PMID 31922014, 2018). "In addition to increases of TNF-α, significant increases in plasma IL-6 (732.5-fold; p<0.001) and CD40L (8.3-fold; p<0.001) were observed in AOM-treated mice at coma stages of encephalopathy." (PMID 23166746, 2012). "It is believed that elevated IL-6 precedes neurological symptoms, and thus may not necessarily be elevated during or after encephalopathy." (PMID 35058867, 2021). "Previous literatures have revealed that IL-6 and IL-1β showed significant correlations with PHES score and correlate with health-related quality of life irrespective of MHE Serum IL-6 and IL-18 levels are reported to be correlated with the degree of encephalopathy." (PMID 26039496, 2015).
Encephalopathy (continued). "We also showed that CSF IL-6 and TNF-α levels were elevated only in the HHV-6 encephalopathy group, but not in the HHV-6 complex FS group." (PMID 25294958, 2014).
non-alcoholic fatty liver disease (61 papers, 2011 to 2026). "Overall, the results of this Mendelian randomization research indicated that IL-6R blockage may raise the risk of non-alcoholic fatty liver disease by blocking the IL-6 signaling pathway." (PMID 38535313, 2024). "Further, P. gingivalis decreased insulin sensitivity and increased pro-inflammatory cytokines TNF-α and IL-6, causing an inflammatory response in the liver by lipid droplet formation indicating that periodontitis may affect nonalcoholic fatty liver disease (NAFLD;)." (PMID 33504065, 2021). "In non-alcoholic fatty liver disease, SalB reduces the expression levels of NF-κB p65, IL-6, and TNF-α in the liver, mitigating liver damage." (PMID 39459158, 2024). "Markers of liver inflammation such as interleukin-6 (IL-6) and tumor necrosis factor alpha (TNFα), which are important in the progression of non-alcoholic fatty liver disease to non-alcoholic steatohepatitis were decreased by NCT." (PMID 35087037, 2022). "For instance, in “Non-alcoholic fatty liver disease” pathway, IL6 activates its receptor IL6R and regulates the activity of lipogenic enzymes through SOCS3 and SREBP-1c to influence de novo fatty acid synthesis." (PMID 35237299, 2022). "Although the involvement of myokines in lipid metabolism in adipocytes was previously discussed, little is known about the direct relationship between nonalcoholic fatty liver disease and muscle-derived IL-6." (PMID 34576053, 2021). "Mice exposed to PM2.5 has been demonstrated to have increased mRNA expressions of inflammatory cytokines such as TNFα, IL-6 and exhibited Non-alcoholic fatty liver disease (NAFLD)." (PMID 33953864, 2021). "The associations between serum levels of melatonin and concentrations of tumor necrosis factor (TNF)-a and interleukin (IL)-6 were assessed among patients with different degrees of non-alcoholic fatty liver disease." (PMID 34221262, 2021). "IL-6 may also show potential in the diagnosis of non-alcoholic fatty liver disease with metabolic dysfunction, as well as in complications related to the urinary system, regardless of sex." (PMID 39769504, 2024). "Furthermore, caffeine-stimulated skeletal muscle IL-6 production alleviated nonalcoholic fatty liver disease (NAFLD) in a rodent model." (PMID 36570495, 2022). "Adipokines, such as tumor necrosis factor alpha, IL‐6, leptin, and adiponectin produced by adipose tissue, are closely involved with hepatic lipid deposition, inflammation, fibrosis, and carcinogenesis in nonalcoholic fatty liver disease." (PMID 34463983, 2021). "Other pathways include pathways in cancer (IL6 and AKT1), non-alcoholic fatty liver disease (AKT1 and IL1B), and the CAMP signaling pathway (AKT1)." (PMID 41601963, 2026). "The flavonoid hesperidin significantly enhances GLP-1 secretion and reduces pro-inflammatory biomarkers such as IL-6, TNF-α, and hsCRP in both clinical and preclinical models of non-alcoholic fatty liver disease." (PMID 40904779, 2025). "In another study, it was reported that the relative abundance of Lachnoclostridium contributed to dysbiosis and was positively correlated with IL‐6, TNF‐α and cholesterol levels in mice with a high‐fat diet and nonalcoholic fatty liver disease model." (PMID 39620016, 2024). "Aucubin also prevented the elevation of MMP-9, MCP-1, apoC-III, ICAM-1, VCAM-1, TNF-α, IL-1β, and IL-6 levels after stimulation by apoC-III in 3T3-L1 cells and in mice with tyloxapol-induced nonalcoholic fatty liver disease (NAFLD)." (PMID 37241895, 2023). "In a study on rats with non-alcoholic fatty liver disease, 200 mg/day propolis reduced TNF-α and IL-6, with effects attributed to the anti-inflammatory activity of propolis." (PMID 31717277, 2019).
non-alcoholic fatty liver disease (continued). "Inflammatory factors, including tumor necrosis factor-α (TNF-α), interleukin-1 β (IL-1β), interleukin- 6 (IL-6), transforming growth factor-β (TGF-β), are involved in drug-induced liver injury, cholestasis, alcoholic and non-alcoholic fatty liver diseases, and other chronic liver disease processes." (PMID 34366845, 2021). "We identified the lncRNA uc.333 using an lncRNA microarray and then used quantitative real-time polymerase chain reaction to analyze its expression in the livers of nonalcoholic fatty liver disease (NAFLD) patients, db/db mice, high-fat diet–fed mice, IL-6-treated mice, and TNF-α-treated mice." (PMID 32303004, 2020). "Elevated ALT/AST levels directly correlate with insulin resistance in non-alcoholic fatty liver disease (NAFLD) through impaired hepatic lipid metabolism, while in alcoholic liver injury, they reflect amplified pro-inflammatory cytokine production (TNF-α, IL-6) and neutrophil infiltration." (PMID 40978853, 2025). "According to previous reports, AMPK activation is involved in the inhibition of the IL-6-stimulated inflammatory response in human liver cells and mediates the antioxidant stress ability of fibroblast growth factor (FGF) one in a mouse model of nonalcoholic fatty liver disease." (PMID 34531748, 2021). "Previous studies have indicated that variants of the high sensitive C-reactive protein (CRP), Interleukin (IL)-6 and leptin receptor (LEPR) genes are associated with the presence of obstructive sleep apnea (OSA) but not in non-alcoholic fatty liver disease (NAFLD) in Asian Indians." (PMID 30001365, 2018). "Although inflammation is a suggested feature of non-alcoholic fatty liver disease (NAFLD), data on circulating levels of interleukins in NAFLD are rather scarce, but increased levels of IL-6 and IL-8, but not IL-18, have been reported in individuals with NAFDL." (PMID 33604566, 2021).
Hyponatremia (60 papers, 2015 to 2025). An abnormally decreased sodium concentration in the blood. "Later explanations for the cause of hyponatremia included increased serum interleukin-6 levels, centrally induced hypocortisolism, vomiting, diarrhea, intestine cell damage, and kidney involvement with proximal tubulopathy." (PMID 38592301, 2024). "Many studies have demonstrated that IL-6-mediated hyponatremia is associated with a variety inflammatory conditions including head injuries, bodily injury in traffic accidents, and autoimmune diseases, as well as in prolonged exercise." (PMID 39797178, 2024). "The pathogenesis of hyponatremia is associated with pro-inflammatory cytokines, such as interleukin-6 (IL-6) and interleukin 1 beta." (PMID 37838701, 2023). "The exact etiology of hyponatremia in COVID-19 is unclear, however, inflammatory cytokines such as interlukein-1β and IL-6 induce secretion of arginine vasopressin which can cause the syndrome of inappropriate ADH secretion (SIADH) and thus hyponatremia." (PMID 37744432, 2023). "In a study on Kawasaki disease, elevated CRP was associated with elevated IL-6, elevated IL-1β, and subsequently rates of hyponatremia." (PMID 37744432, 2023). "After adjustment for age, diagnosis of hyponatremia and serum IL-6 levels was associated with a worse lung involvement at admission (expressed by a RALE score 5) at multivariable logistic regression analysis (p = 0.014)." (PMID 36284058, 2023). "It has also been reported that CRP, IL-6, IL-1β, and neutrophil counts are associated with hyponatremia." (PMID 35356251, 2022). "Adding to that, CRP, an end-product of the IL-6 inflammatory pathway, was tied with an increased risk of hyponatremia." (PMID 36714113, 2022). "The pathogenesis behind the association of complicated appendicitis and hyponatremia remains uncertain, but new evidence suggests IL-6 has a role in osmoregulation in intra-abdominal inflammation, leading to release of vasopressin." (PMID 35884054, 2022). "IL-6-stimulated AVP secretion in euvolemic children has been shown to cause hypo-osmolar hyponatremia." (PMID 31670650, 2020). "Further studies will be needed to confirm a causative relationship between IL-6 levels and hyponatremia following CD19+ CAR T-cell infusion." (PMID 31670650, 2020). "Of note, coronavirus disease 2019 (COVID-19), which seems to affect the hematopoietic system (e.g., lymphopenia, coagulopathy) has also been associated with IL-6-related hyponatremia." (PMID 33228240, 2020). "CD19 + CAR T-cells used for the treatment of relapsed/refractory ALL may cause hyponatremia due to hypercytokinemia and elevated IL-6, which stimulates the hypothalamus for the inappropriate release of ADH." (PMID 33228240, 2020). "In contrast to known stimuli (serum osmolality, hemodynamic changes), IL-6 may cause vasopressin (antidiuretic hormone) release as a secondary messenger, leading to hyponatremia." (PMID 31764808, 2019). "Recent research revealed that inflammatory cytokines such as interleukin (IL)−1β and IL-6 are involved in the development of hyponatremia associated with inflammatory conditions, and they might be related to ADH secretion." (PMID 30405154, 2018). "IL-6 may induce hyponatremia by causing vasopressin release." (PMID 35801207, 2022). "Furthermore, preliminary data show an inverse association between serum sodium and interleukin-6 levels, suggesting that hyponatraemia might be used as a surrogate marker for the risk of a cytokine storm and the need for treatment with interleukin antagonists." (PMID 34370712, 2021). "In this case, the patient presented with fever and headache, infection-related markers such as elevated white blood cell count, neutrophil percentage, and IL-6 levels, along with persistent hyponatremia." (PMID 40718417, 2025). "Laboratory analysis reveals the same chemical profile in patients with classic ectopic SIADH and patients with IL-6-induced hyponatremia, both of whom are euvolemic with inappropriate ADH secretion." (PMID 39797178, 2024).
Hyponatremia (continued). "This is mainly driven by a high interleukin-6 level, which impairs the osmoregulatory mechanism of ADH in the brain, causing hyponatremia." (PMID 39204294, 2024). "The exact etiology of hyponatremia in those with appendicitis is not well understood, but it has been proposed that interleukin-6 (IL-6) plays a key role." (PMID 35949749, 2022). "The patient was found to have hyponatremia, increased interleukin 6 (IL-6) levels and CSF anti-NMDAR antibodies." (PMID 33803475, 2021). "In the pathogenesis of hyponatremia, interleukin-6 (IL-6) released by monocytes and macrophages plays an important role; it induces the non-osmotic release of vasopressin and secondary electrolyte disturbances." (PMID 33435405, 2021). "Control blood tests documented further increased inflammatory indices (CRP 166 mg/l, PCT 4.1 ng/ml), fibrinogen (640 mg/dl), ferritin (521 ng/ml), IL-6 (70.7 pg/ml), and a worsening hyponatremia (132 mmol/l)." (PMID 34422717, 2021). "This study will evaluate the correlation of IL-6 levels with hyponatremia in patients receiving CD19+ CAR T-cells." (PMID 31670650, 2020). "In ultramarathon runners who experienced exercise-associated hyponatremia (EAH), there was a significant positive correlation between IL-6 and AVP levels." (PMID 31670650, 2020). "The aims of this study are to report on the rate of hyponatremia in patients who have received CD 19+ CAR-T cell therapy and to examine the relationship between IL-6 levels and hyponatremia." (PMID 31670650, 2020). "Further studies are required in order to clarify the relationship of hyponatremia, IL-6, β2MG, and reversible SCC lesions." (PMID 31764808, 2019). "In fact, an association between Interleukin-6 and arginine vasopressin has been observed, considering interleukin-6 to be the principal stimulator of arginine vasopressin in marathon runners with hyponatremia." (PMID 31455034, 2019). "We observed a transcient hyponatremia that serum sodium fell to 118 mmol/L as well as the remarkable elevation of serum IL-6 at the beginning of the disease on our patient." (PMID 30045281, 2018). "Thirdly, elevated expression of IL-6, acting as a second messenger to trigger the release of vasopressin, has been hypothesized to be involved in the development of hyponatremia." (PMID 39430766, 2024). "To this end, we measured TNFα and Il6 levels in hyponatremia patients." (PMID 37992803, 2023). "Although antidiuretic hormone released by proinflammatory cytokines such as IL-6 induces hyponatremia, serum sodium levels could rise due to many variable factors, such as dehydration, vomiting, extreme diarrhea, or fever." (PMID 36900066, 2023). "Hyponatremia may also be a consequence of the increased inflammatory biomarkers and interleukin (IL)-6 being one of the most relevant cytokines involved in COVID-19 infection." (PMID 35801207, 2022). "Infection can cause excess release of proinflammatory cytokines, such as interleukin-1β and interleukin-6 (IL-6), which induce nonosmotic release of arginine vasopressin, causing hyponatremia due to SIAD." (PMID 33624101, 2021). "In order to advance our understanding of the link between inflammatory response and hyponatraemia, prospective studies are warranted to examine longitudinally the serum IL-6 levels, serum sodium concentration, inflammatory markers, and severity of the clinical condition." (PMID 34370712, 2021). "IL-6, TNF-α as well as other cytokines participate in inflammation of KD patients in the acute phase, suggesting that hyponatremia may be associated with inappropriate release of ADH." (PMID 31921727, 2019). "Serum IL-6 remarkably elevated, and hyponatremia appeared on day 2 of hospitalization." (PMID 30045281, 2018). "In addition to standard biomarkers, several new biomarkers for acute appendicitis, such as hyponatremia, hyperfibrinogenemia, hyperbilirubinemia, pentraxin-3 (PTX-3), neutrophil gelatinase-associated lipocalin (NGAL), or interleukin-6 (IL-6), have recently been investigated." (PMID 37189999, 2023).